GABRG1 (gamma-aminobutyric acid type A receptor subunit gamma1)
Description:
Gamma subunit of the heteropentameric ligand-gated chloride channel gated by gamma-aminobutyric acid (GABA), a major inhibitory neurotransmitter in the brain. GABA-gated chloride channels, also named GABA(A) receptors (GABAAR), consist of five subunits arranged around a central pore and contain GABA active binding site(s) located at the alpha and beta subunit interface(s) (By similarity). When activated by GABA, GABAARs selectively allow the flow of chloride anions across the cell membrane down their electrochemical gradient. Chloride influx into the postsynaptic neuron following GABAAR opening decreases the neuron ability to generate a new action potential, thereby reducing nerve transmission (By similarity).
Tractability: Small molecule: an approved drug acts on it; a high-quality ligand is known; it belongs to a druggable protein family. Antibody: its Gene Ontology location is reachable by antibodies, with high confidence; UniProt places it where antibodies can reach, with medium confidence; UniProt predicts a signal peptide or a membrane-spanning region; the Human Protein Atlas places it where antibodies can reach. PROTAC: a small molecule that binds it is known.
Safety:
Unwanted effects reported when the protein is acted on. In parentheses: how it was acted on, where the effect was seen, and who reports it.
ataxia (activation, acute dosing; central nervous system, cardiovascular; source: Lynch et al. (2017))
convulsions (inhibition, acute dosing; central nervous system, cardiovascular; source: Lynch et al. (2017))
decreased anxiety (activation, acute dosing; central nervous system, cardiovascular; source: Lynch et al. (2017))
decreased blood pressure (activation, acute dosing; central nervous system, cardiovascular; source: Lynch et al. (2017))
decreased body temperature (activation, acute dosing; central nervous system, cardiovascular; source: Lynch et al. (2017))
decreased cardiac contractility (activation, acute dosing; central nervous system, cardiovascular; source: Lynch et al. (2017))
decreased convulsions (activation, acute dosing; central nervous system, cardiovascular; source: Lynch et al. (2017))
decreased locomotor activity (activation, acute dosing; central nervous system, cardiovascular; source: Lynch et al. (2017))
decreased memory (activation, acute dosing; central nervous system, cardiovascular; source: Lynch et al. (2017))
decreased pain (activation, acute dosing; central nervous system, cardiovascular; source: Lynch et al. (2017))
decreased sleep (inhibition, acute dosing; central nervous system, cardiovascular; source: Lynch et al. (2017))
drug abuse/dependence (activation, acute dosing; central nervous system, cardiovascular; source: Lynch et al. (2017))
increased cardiac output (activation, acute dosing; central nervous system, cardiovascular; source: Lynch et al. (2017))
increased eating (activation, acute dosing; central nervous system, cardiovascular; source: Lynch et al. (2017))
increased respiratory rate (activation, acute dosing; central nervous system, cardiovascular; source: Lynch et al. (2017))
increased sleep (activation, acute dosing; central nervous system, cardiovascular; source: Lynch et al. (2017))
muscle relaxation (activation, acute dosing; central nervous system, cardiovascular; source: Lynch et al. (2017))
Gene: Protein-coding gene on chromosome 4 (46,035,769 to 46,124,054, reverse strand). Ensembl gene ENSG00000163285.
Subcellular location: Postsynaptic cell membrane; Cell membrane
Subcellular location (Human Protein Atlas): Plasma membrane; Vesicles
Gene Ontology:
Molecular function: protein binding; GABA-A receptor activity; extracellular ligand-gated monoatomic ion channel activity; GABA receptor binding; monoatomic ion channel activity; transmembrane signaling receptor activity
Biological process: chloride transmembrane transport; inhibitory synapse assembly; synaptic transmission, GABAergic; chloride transport; gamma-aminobutyric acid signaling pathway; monoatomic ion transmembrane transport; monoatomic ion transport
Cellular component: plasma membrane; dendrite membrane; GABA-A receptor complex; postsynapse; membrane; postsynaptic membrane; receptor complex
Genetic constraint (gnomAD): Loss-of-function variants: 35 observed, 35.4 expected, observed/expected ratio (o/e) 0.99, 90% interval 0.75 to 1.31. The upper end of that interval is the gene's LOEUF score, 1.31, which puts it in group 5 of 6, group 1 being the genes least tolerant of losing a copy. Missense variants: 427 observed, 439.92 expected, observed/expected ratio (o/e) 0.97, 90% interval 0.9 to 1.05. Synonymous variants: 179 observed, 156.6 expected, observed/expected ratio (o/e) 1.14, 90% interval 1.01 to 1.29.
Homologues: Orthologues: chimpanzee GABRG1 (100% identical), dog GABRG1 (96% identical), macaque GABRG1 (95% identical), pig GABRG1 (95% identical), rabbit GABRG1 (95% identical), mouse Gabrg1 (95% identical), rat Gabrg1 (95% identical), guinea pig GABRG1 (79% identical), zebrafish gabrg1 (74% identical). Paralogues in human: GABRG2 (74% identical), GABRG3 (66% identical), GABRA6 (45% identical), GABRA1 (43% identical), GABRA4 (43% identical), GABRA3 (43% identical), GABRA5 (43% identical), GABRE (42% identical), GABRA2 (42% identical), GABRB2 (34% identical), GABRB1 (34% identical), GABRB3 (34% identical), and 33 more.
Diseases named in the same sentence as GABRG1 in open-access papers:
GABRG1 is named in the same sentence as 23 diseases in open-access papers, as found by Europe PMC text mining. Sharing a sentence is not in itself a finding about the gene and the disease. The quoted sentences say what the papers report.
alcohol dependence (5 papers, 2012 to 2024). Physical and psychological dependence on alcohol. "Of the three GABA receptors examined, strain differences were most prominent for Gabrg1 (Gamma-Aminobutyric Acid Type A Receptor Subunit Gamma1), which has been implicated in epilepsy and alcoholism, as well as with depression and suicide behavior." (PMID 38727295, 2024). "COGA studies had linked alcohol dependence with the GABAA receptor gene family region that contains GABRG1 in the chromosome 4p." (PMID 24312204, 2013). "Other genes and gene families showing monoallelic expression include the annexin gene family and the Thy1 gene, both linked to inflammation and cancer, as well as genes linked to alcohol dependence (Gabrg1) and epilepsy (Kcnma1)." (PMID 22384067, 2012). "In support of Gabra2-Gabrb1 covariance in expression, a GABRA2 risk variant for alcohol dependence leading to reduced expression of GABRA2 positively correlated with expression of GABRB1, GABRG1 and GABRA4 in human iPSCs." (PMID 34677900, 2021). "Changes specific to alcoholism were the down-regulation of GABRA2 (FDR p = 0.028) and a trend down-regulation of GABRG1 (FDR p = 0.056)." (PMID 22253714, 2012).
Anxiety (3 papers, 2016 to 2023). Intense feelings of nervousness, tension, or panic often arise in response to interpersonal stresses. "We observe significant enrichment of NTSR2, GPR88 and Gabrg1 in chloroquine-activated neurons, and relatively lower expression of OPRM1, PENK and Chrm1, suggesting that these genes could be critical candidates in regulating pruritis and its associated anxiety." (PMID 34032210, 2021). "Thus, natural GABRG1 knock-out pigs carrying this stop codon may show both signs of anxiety and a particular eating behaviour." (PMID 27566279, 2016).
autism (3 papers, 2022 to 2025). Persistent deficits in social interaction and communication and interaction as well as a markedly restricted repertoire of activity and interest as well as repetitive patterns of behavior. "The largest shortlisted variant is a homozygous Del (2.2 kb) in the intronic region of GABRG1 in the Jordanian proband who has seizures and autism." (PMID 40325133, 2025).
glioma (2 papers, 2024). A benign or malignant brain and spinal cord tumor that arises from glial cells (astrocytes, oligodendrocytes, ependymal cells). "In patients with lower grade gliomas, GABRA3, GABRB3, GABRG1, and GABRG2, were associated with longer OS." (PMID 38539663, 2024). "We previously reported that high levels of GABRA2, GABRA3, GABRB3, GABRG1, and GABRG2 indicated better prognosis in glioma, and GABRB3 was particularly associated with longer OS in patients with lower-grade gliomas." (PMID 39595908, 2024).
Stroke (2 papers, 2020 to 2024). Sudden impairment of blood flow to a part of the brain due to occlusion or rupture of an artery to the brain. "When GABRG1 function is compromised, it can lead to heightened neural excitation, potentially resulting in post‐stroke spasticity." (PMID 39099086, 2024).
colon cancer (1 paper, 2024). "However, irrespective of whether expression of GABAA or GABAB receptor subunits were altered in colon cancer, expression of particular receptor subtypes (GABRA1, GABRA5, GABRD, GABRE, GABRG1, GABRG3, GABBR1, and GABBR2) was significantly associated with poor clinical outcome." (PMID 38886975, 2024).
itch (1 paper, 2021). "We observed considerable overlap between NTSR2+ve (75.31% cells), GPR88+ve (69.35%) and Gabrg1+ve (62.32% cells) cells with itch-activated Fos+ve cells in the CeA." (PMID 34032210, 2021).
lung adenocarcinoma (1 paper, 2014). A carcinoma that arises from the lung and is characterized by the presence of malignant glandular epithelial cells. "We identified alterations in genes involved in chromatin remodeling (PBRM1, SETD2), oxidative stress (CUL3, SOD2), immune response (CSMD3, SYK), and gamma-aminobutyric acid receptor signaling (GABRD, GABRG1) in lung adenocarcinoma." (PMID 24576404, 2014).
cancer (4 papers, 2012 to 2025). A tumor composed of atypical neoplastic, often pleomorphic cells that invade other tissues. "Throughout cancer staging, TCGA database showed consistent reduction in expression levels of GABRA2, GABRE, GABRG1 and GABRP by up to 32.7%, 18.7%, 15.4% and 5.9%, respectively." (PMID 40583063, 2025). "The relationship between GABRG1 and cancer has not yet been reported." (PMID 31467637, 2019).
GABRG1 also shares sentences with these, for which no sentence is quoted: epilepsy (3 papers); tumor (3); alcoholism (2); breast carcinoma (2); cocaine addicts (1); cognitive deficits (1); depression (1); Intellectual disability (1); lung carcinoma (1); medulloblastoma (1); migraines (1); neurodegenerative disease (1); schizophrenia (1); type 2 diabetes (1).